TEX48 (testis expressed 48)
Gene: Protein-coding gene on chromosome 9 (114,666,434 to 114,682,192, reverse strand). Ensembl gene ENSG00000230601.
Gene Ontology:
Molecular function: protein binding
Genetic constraint (gnomAD): Loss-of-function variants: 10 observed, 10.73 expected, observed/expected ratio (o/e) 0.93, 90% interval 0.57 to 1.56. The upper end of that interval is the gene's LOEUF score, 1.56, which puts it in group 6 of 6, group 1 being the genes least tolerant of losing a copy. Missense variants: 98 observed, 111.68 expected, observed/expected ratio (o/e) 0.88, 90% interval 0.74 to 1.04. Synonymous variants: 35 observed, 40.14 expected, observed/expected ratio (o/e) 0.87, 90% interval 0.67 to 1.16.
Homologues: Orthologues: chimpanzee TEX48 (96% identical), macaque TEX48 (93% identical), rabbit TEX48 (66% identical), dog TEX48 (61% identical), pig TEX48 (58% identical), mouse Tex48 (48% identical), rat Tex48 (47% identical).
Diseases named in the same sentence as TEX48 in open-access papers:
TEX48 is named in the same sentence as 2 diseases in open-access papers, as found by Europe PMC text mining. Sharing a sentence is not in itself a finding about the gene and the disease. The quoted sentences say what the papers report.
cancer (1 paper, 2024). A tumor composed of atypical neoplastic, often pleomorphic cells that invade other tissues. "Studying the molecular pathways responsible for TEX48 dysregulation in CC may also lead to new treatment options for this cancer." (PMID 39208330, 2024).
TEX48 also shares sentences with these, for which no sentence is quoted: colon cancer (1 paper).